EIF3IP1 (eukaryotic translation initiation factor 3 subunit I pseudogene 1)
Synonyms: RG208K23
Gene: Processed pseudogene on chromosome 7 (109,959,218 to 109,960,184, reverse strand). Ensembl gene ENSG00000237064.
Diseases named in the same sentence as EIF3IP1 in open-access papers:
EIF3IP1 is named in the same sentence as 1 disease in open-access papers, as found by Europe PMC text mining. Sharing a sentence is not in itself a finding about the gene and the disease.
EIF3IP1 shares sentences with these, for which no sentence is quoted: gout (1 paper).